PGR (progesterone receptor)
Diseases named in the same sentence as PGR in open-access papers (continued):
Sharing a sentence is not in itself a finding about the gene and the disease.
tumor (continued). "Immunohistochemistry corresponds to typical sex cord-stromal tumour profile (positivity for SF1, calretinin, inhibin, vimentin, often FOXL2; often oestrogen and progesterone receptor expression; and negativity or weak patchy staining for keratin, negativity for EMA, PAX8, and PAX2)." (PMID 36399188, 2023). "In 369 (92%) of 400 patients with tumours expressing only one hormone receptor, the progesterone receptor was the absent receptor." (PMID 36992863, 2023). "Established associations of Ki67baseline with biologic factors including PgR status, tumour grade, tumour size, histological subtype, nodal status, and vascular invasion were confirmed in the HER2- subpopulation." (PMID 37046348, 2023). "Of note, the tumor of patient RNA-1 had only 20% of ER-positive cells, as well as a low abundance of ESR1 and PGR transcripts, which could explain its poor response to endocrine treatment (List S1)." (PMID 36574653, 2023). "Tumor cells showed immunoreactivity for β-catenin, progesterone receptor and vimentin, and were negative to synaptophysin immunostaining." (PMID 38132247, 2023). "In addition, PGR, as well as UGT2B15 and UGT2B7, which were the non-tumor-related genes identified among the 29 targeted genes, were found to be related to overall survival in CRC patients." (PMID 36843944, 2023). "We found a positive correlation of HK2 expression levels with larger tumor sizes, progesterone receptor (PR)-negative expression, and higher Ki67 levels." (PMID 37377974, 2023). "The level of progesterone receptor (PGR) expression in CRC tissues correlates with sex, tumor size, degree of differentiation of the tumors, degree of infiltration of the tumor vasculature, and tumor clinical stage." (PMID 38115900, 2023). "Further studies found that the presence of PIP in breast tumors positively correlated with estrogen receptor negative (ER-) and progesterone receptor (PR)-positive status, a low tumor grade, and long relapse-free survival." (PMID 37085653, 2023). "We also detected five mutations (ALOX2B, JAK1, PGR, RUNX1, SOX1) in the HGSOC41.1 tumor sample but not in the corresponding PDO." (PMID 37202753, 2023). "In female cancerous specimens, both ERβ and PGR exhibited weak to moderate negative correlations with tumor size, N stage, perineural invasion, and late-stage malignancy." (PMID 37206439, 2023). "The tumor cells displayed a lack of reactivity for estrogen receptor (ER), progesterone receptor (PR), and human epidermal growth factor receptor-2 (HER2), and exhibited a Ki-67 proliferation index of approximately 40%." (PMID 38196420, 2023). "EPA and DHA carried by apo B-containing lipoproteins (Non-High-Density Lipoprotein (HDL)) showed a protective effect on tumor cell proliferation only in tumors negative for ER and PgR, comparing different lipoproteins and the degree of severity of BC in women." (PMID 36986040, 2023). "To characterize this cohort with stage I TNBC tumors, we evaluated patient DFS, OS, and background (age, tumor size, NG, HER2/ER/PgR status, surgical procedure, and whether adjuvant radiotherapy or chemotherapy was administered)." (PMID 37051545, 2023). "Groups L3 and L4 cells derived from the tumor zone and had low expressions of ESR1/PGR/HER2." (PMID 37644609, 2023). "Triple negative breast cancer (TNBC) is defined as the absence of tumor tissue expression of the estrogen receptor (ER), progesterone receptor (PR) and the human epidermal growth factor receptor 2 (HER2)." (PMID 37925462, 2023). "TNBC is defined as a tumor lacking the expression of estrogen receptor, progesterone receptor and HER2, so there is no targeted therapy and hormone therapy available." (PMID 36394035, 2022). "Discordance was observed in larger sized tumours (>20mm) and oestrogen receptor/progesterone receptor (ER/PR) negative tumours (3 of 4 patients)." (PMID 36256643, 2022).
tumor (continued). "This type of heterogeneous tumor shows no expression of estrogen receptor (ER) or progesterone receptor (PR) and does not express the HER2 gene, and often these tumors are high grade with distinct histological groups." (PMID 36120232, 2022). "We did not have information on the degree of positivity of tumor estrogen and progesterone receptor expression or on results of the 21-gene recurrence score assay, if performed." (PMID 35723570, 2022). "In contrast, the data indicated that very little responsiveness below a cut-point of 40% for PgR − tumours, irrespective of the use of a 1% or 10% cut-point for PgR positivity." (PMID 36096872, 2022). "In current clinical practice, breast cancers are classified in five subtypes based on the expression of hormone receptors (estrogen and/or progesterone receptors (ER and/or PgR)), the overexpression of epidermal growth factor receptor 2 (HER2/Neu) and the percentage of tumor cells expressing Ki-67." (PMID 36010869, 2022). "In terms of immunohistology, poor prognostic factors, including a large tumour size (≥ 2 cm), negative ER status, negative PgR status, high Ki67%, and high histological grade, are correlated with high SUVmax." (PMID 35768684, 2022). "Of these 122 tumours, 89 were estrogen receptor positive and 33 estrogen receptor negative, whereas 76 were progesterone receptor positive and 46 were progesterone receptor negative." (PMID 34510244, 2022). "Across all five pivotal trials, “positive HR status” is defined as either ER or PgR positivity, with no data reported for ER-positive/PgR-positive and ER-positive/PgR-negative tumours." (PMID 35833190, 2022). "Among PgR − tumours, there were no GRs with relative ER qPCR expression < 20 and among PgR + tumours GRs occurred with relative ER qPCR as low as 5–10." (PMID 36096872, 2022). "The standard approach to date is based on targeting the HER2 receptor in combination with chemotherapy irrespective of the estrogen and progesterone receptor status of the tumor." (PMID 35013314, 2022). "ER does not function sufficiently in some PgR negative cases and the tumor is therefore no longer dependent on estrogen for growth and survival." (PMID 35566456, 2022). "While we did not investigate the latent classes and age cohort separately for each individual tumor stage or estrogen and progesterone receptor statuses (negative, positive), we controlled for significant clinical covariates." (PMID 35547250, 2022). "Immunohistochemistry revealed tumor cells positive for estrogen receptor (ER) and progesterone receptor (PgR) and no amplification of the HER2 gene." (PMID 35300738, 2022). "The characteristics of these molecular subtypes are largely distinguished by expression of various combinations of tumour markers such as oestrogen receptor (ER), progesterone receptor (PR), human epidermal growth factor receptor-2 (HER2) and Ki67 tumour proliferation marker." (PMID 36116093, 2022). "In contrast, PAD4 has been shown to promote progression in triple-negative breast cancer (TNBC), a tumor lacking estrogen receptor, progesterone receptor (PR), and human epidermal growth factor receptor type 2 (HER2) expression." (PMID 36365233, 2022). "The results obtained in this study indicated that education, hormone therapy, estrogen and progesterone receptor status, and tumor grade were not significantly affecting the overall survival of neoadjuvant and adjuvant groups." (PMID 36536751, 2022). "The results of the present study revealed that the expression of ESR1 and PGR correlated with the tumor stage, whereas the expression of ESR2 did not." (PMID 34322374, 2021). "If it resembles the pattern of other steroid receptors as ER and PgR, the concordance of TMA and whole tumor slides could be approximated to around 90%." (PMID 34930399, 2021).
tumor (continued). "We therefore examined the expression of ER, PgR, HER2, Ki67, and tumor-infiltrating lymphocytes (TILs), as well as nuclear and histological grades, in tumor specimens from patients enrolled in these two studies using the currently available measurement methods." (PMID 33259001, 2021). "Importantly, scRNAseq identified PGR and IRS-1 enrichment in metastases compared to primary tumours, whereas IGF1R expression trended downward in metastases." (PMID 33144693, 2021). "Histological features and expression of PgR and ER in ACC tumor specimens." (PMID 33981288, 2021). "Immunostaining of the resected specimen indicated that the tumor was estrogen receptor-positive, progesterone receptor-negative, human epithelial growth factor receptor 2-positive, and the Ki-67 labeling index was 70%." (PMID 33482449, 2021). "The tumor was estrogen and progesterone receptor-positive and Her2/neu-negative and had a Ki-67 labeling index of 20%." (PMID 34495428, 2021). "In the no NAC group, menopausal status, tumor size over 2 cm, a higher histologic grade, and ER/PgR negativity were found to affect HER2 discrepancy in univariate analysis." (PMID 34149935, 2021). "Another study showed the impact of H3K27me3 on the regulation of the Retinoic acid receptor β2 (RARβ2), estrogen receptor (Erα), progesterone receptor (PGR), and Repulsive Guidance Molecule A (RGMA) genes and also correlated H3K27me3 with the level of tumor aggressivity." (PMID 33478063, 2021). "Immunohistochemical study of the different lesions was performed and both primary tumor and regional metastasis showed tumor cells to be negative estrogen receptor alpha, positive progesterone receptor, positive HER-2, and positive pan-cytokeratin." (PMID 34064434, 2021). "TNBC is defined by the expression of 1% or less of estrogen receptor (ER) and progesterone receptor (PR) in the tumor, along with the absence of HER2 amplification." (PMID 33413403, 2021). "Immunohistochemically, the tumor cells are generally estrogen receptor (ER) and progesterone receptor (PR) negative, and do not show amplification or overexpression of human epidermal growth factor receptor 2 (HER2)." (PMID 34629079, 2021). "More specifically, HDAC-2 and HDAC-3 proteins were correlated with a lower grade of tumor differentiation and negative estrogen receptor (ER) and progesterone receptor (PR) status." (PMID 34441281, 2021). "High PODXL has also been associated with poor tumour differentiation and estrogen- and progesterone-receptor-negative tumours." (PMID 34201212, 2021). "The tumor was estrogen and progesterone receptor-positive, Her2/neu-negative, and had a Ki-67 labeling index of 20%." (PMID 34495428, 2021). "Moreover, ERa, ERb, and PGR proteins were highly expressed in 42.9%, 50%, and 21.4% of OV tumor samples and in 64.7%, 35.3%, and 60.8% of UTEA tumor samples, respectively." (PMID 34322374, 2021). "The benefit was maintained across subgroups, including patients with poorer prognosis, such as presence of liver metastases, PgR-negative tumors, high tumor grade, and TFI < 36 months." (PMID 34158513, 2021). "Typically, tumours are luminal in molecular subtype, being oestrogen and progesterone receptor positive, and HER2 negative." (PMID 33413533, 2021). "This tumor has few PgR IR cells with faint staining intensity with no ER expression and moderate proliferation index." (PMID 33981288, 2021). "Consistent with previous studies on evaluating the risk factors of DM in patients with invasive breast cancer, patients with tumor size (>10 mm), ILC, estrogen receptor (ER), and progesterone receptor (PR) as well as Her-2-positive subtype, and Black race presented a higher risk of DM." (PMID 34899606, 2021).
tumor (continued). "For instance, most of the tumors ER and PgR status considered to be negative had IHC expression scores <10%, although the most recent guidelines recommend considering tumor samples with 1% or more nuclei positive as ER-positive." (PMID 34198891, 2021). "Moreover, progesterone receptor (PR) and ER expression were identified by all PET-positive primary tumours (13/13) compared to 1/5 PET-negative tumour." (PMID 33925632, 2021). "Lymph node involvement, pathological tumor size, histological grade, ER and PgR status, HER2 status, and proliferation index were not significantly different among these two groups." (PMID 34869002, 2021). "The tumor markers reported; Positive Estrogen Receptor (ER+), negative Progesterone Receptor (PR-), and negative Human Epidermal Receptor (HER-)." (PMID 34934489, 2021). "In this paper, we identified nine novel tumor types from TCGA with FAM83H-AS deregulation, and used a multivariate Cox regression analysis to demonstrate that FAM83H-AS1 expression is a marker for poor survival in Progesterone receptor (PR) positive BRCA." (PMID 32839509, 2020). "Since ER and progesterone receptor (PR) are also negative in this type of tumors, this group is called basal-like or triple negative tumor group." (PMID 32707666, 2020). "Luminal B tumors have lower levels of ER expression, lower or no levels of progesterone receptor (PR) expression, but higher tumor grade and higher Ki-67–positive staining than luminal A tumors." (PMID 33364954, 2020). "Immunohistochemistry showed that tumor cells were 100% positive with moderate-strong intensity for estrogen receptor, negative for progesterone receptor, 5% Ki-67 positive and had an HER2 score of 3+." (PMID 32871976, 2020). "The tumor had an ER-positive, PgR-negative, and HER2-negative biological phenotype, while the Ki-67 labeling index was approximately 30%." (PMID 32562013, 2020). "Correspondingly, a strong correlation of high TTLL4 levels and the lack of estrogen and progesterone receptor in tumour tissue was found (p < 0.001 and p = 0.001, respectively)." (PMID 32998758, 2020). "In immunohistochemistry the tumor was triple-negative with absent staining for estrogen receptor, progesterone receptor and HER2." (PMID 32468491, 2020). "This tumor, classified as basal-like cancer on the basis of its morphology, does not express the estrogen receptor (ER), the progesterone receptor (PR), and the human epidermal growth factor receptor 2 (HER2) negative (neu) markers." (PMID 31938038, 2020). "On the other hand, ER- cases preferentially had greater tumor size and histological grade, higher levels of Ki67, all of them were negative for PgR expression and classified as non-luminal-like tumors according to the IHC-surrogate subtype classification." (PMID 32344660, 2020). "The prognostic value of TSR was not modified by age, tumor size, histology, estrogen receptor status, progesterone receptor status, human epidermal growth factor receptor 2 status or lymph node status." (PMID 31901133, 2020). "Like normal counterparts in the corpus uteri, these tumor stromal cells, rather than epithelial cells, expressed estrogen receptor (ER) and progesterone receptor (PR)." (PMID 32164751, 2020). "In one of the tumours DES-ir, ESR1-ir and PGR-ir decreased significantly after 10 days of culture." (PMID 32251338, 2020). "MiRNA profiles of TIF samples belonging to cluster 1 were predominantly from patients with high-grade (grade 3), high-TIL (tumor-infiltrating lymphocytes, + 2|+ 3) tumors, the majority of which were estrogen- and/or progesterone-receptor negative." (PMID 32605588, 2020). "On immunohistochemistry, the tumor was estrogen receptor-positive, and progesterone receptor-positive and Her-2 negative, and had a Ki-67 score of 60%." (PMID 32569161, 2020). "High-risk prognostic factors include estrogen and progesterone receptor negative status, HER2 status, high tumor grade, high TNM, and younger age of the patient." (PMID 33425733, 2020).
tumor (continued). "To date, Oestrogen Receptor (ER), Progesterone Receptor (PgR), human epidermal growth factor receptor 2 (HER2), and Ki67, together with age, tumor size, histological grade, and lymph node engagement still represent the most reliable markers that provide prognostic information." (PMID 32903519, 2020). "In the rat breast precancerous lesions model, high and low dose RYNXC could also significantly reduce genes and proteins expression of ESR1, PGR, PTGS2, EGFR, and Src." (PMID 30906412, 2019). "Because the tumor had low expression of RE and is negative for PgR, we did not recomment adjuvant hormonal treatment." (PMID 31651866, 2019). "Upon immunohistochemical analysis, the tumor cells showed positivity for c-KIT and CD34 and very low positivity for Ki-67 and negativity for actin, desmin, HHF-35, S-100 protein, estrogen receptor (ER), and progesterone receptor (PgR)." (PMID 31410732, 2019). "The 35‐mm tumor expressed estrogen receptors but tested negative for progesterone receptor and epidermal growth factor receptor 2 expression/overexpression." (PMID 31347298, 2019). "Recurrence would probably not occur in the patient described in our case, as the tumor was resectable with ER and PgR expression." (PMID 31410732, 2019). "Second, luminal A CCND1-amplified tumours display gene expression changes consistent with more aggressive tumours, specifically increased MKI67 and decreased PGR gene expression in addition to an overlap in genes differentially expressed in CCND1-amplified luminal B tumours." (PMID 30819233, 2019). "Tumor pathological type, histological (Nottingham) grading, and estrogen or progesterone receptor status separately did not have an effect on the decision of which procedure was chosen." (PMID 31245000, 2019). "Successful tumor growth did not correlate with their hormonal status (ER or PgR), or with metastasis site (liver or lung)." (PMID 31216647, 2019). "It was significantly related to larger tumor size, positive nodal status, higher clinical disease stage, a poor Nottingham prognostic index, and negative estrogen receptor (ER) and progesterone receptor (PR) status." (PMID 30544617, 2018). "The other system (7 prognostic groups with C‐index = 0.7458) was based on tumor size, regional lymph nodes, no distant metastasis, grade, estrogen receptor, progesterone receptor, and age." (PMID 29968970, 2018). "High IL-10 expression was, however, significantly associated with lower tumour grade (P < 0.001), low NPI value (P < 0.001), positive ER (P < 0.001), positive PgR (P < 0.001), negative Her-2 (P = 0.003) as well as non-TN status (P = 0.003)." (PMID 29256156, 2018). "More specifically, enhanced PD-L1 expression goes along with poor prognostic features, such as an increased proliferation index, enlarged tumor size, absence of estrogen receptor (ER) and/or progesterone receptor (PR), Her2 positivity, and a high tumor grade." (PMID 29438316, 2018). "When correlated to tumor progression markers, a slight significant correlation was seen between estrogen receptor and PTEN (IHC and FISH), estrogen receptor and PIK3CA (IHC) as well as between progesterone receptor and PIK3CA (IHC)." (PMID 29739401, 2018). "The aim of this study was to assess the correlations between parameters of DWI and DCE-MRl in IDC of the breast and prognosis or prognostic factors, such as tumor size, histologic grade, lymph nodes metastasis (LNM), estrogen receptor (ER), progesterone receptor (PR), HER2 (c-erb-2), and Ki-67." (PMID 30577820, 2018).